RNU7-29P (RNA, U7 small nuclear 29 pseudogene)
Synonyms: U7.29; LOC124904769
Gene: Small nuclear RNA gene on chromosome 1 (26,602,369 to 26,602,432, reverse strand). Ensembl gene ENSG00000252429.
Homologues: Paralogues in human: U7 (83% identical), RNU7-60P (81% identical), RNU7-171P (80% identical), RNU7-84P (80% identical), RNU7-35P (78% identical), RNU7-57P (78% identical), RNU7-12P (77% identical), RNU7-133P (77% identical), RNU7-13P (77% identical), RNU7-25P (77% identical), RNU7-30P (77% identical), RNU7-52P (77% identical), and 140 more.